CD4 (CD4 molecule)
Diseases named in the same sentence as CD4 in open-access papers (continued):
Sharing a sentence is not in itself a finding about the gene and the disease.
COVID-19 (continued). "Compared to patients developing mild symptoms, CD4+ and CD8+ T cell populations from COVID-19 patients admitted to intensive care units (ICU) show reduced production of IL-2, a cytokine with major functions in enhancing T and B cell proliferation." (PMID 35860236, 2022). "Activated CD4+ and CD8+ T cells exist during active/ongoing COVID-19 and in certain individuals, even after recovery, activated CD8+ T cells persist for over 100 days." (PMID 36003367, 2022). "In this study, we evaluated humoral and cellular immune responses 1 year post-COVID-19, in terms of the binding activities of circulating Abs to SARS-CoV-2-specific proteins, phagocytic capability of circulating Abs, and memory B- and CD4+ T-cell responses." (PMID 35392102, 2022). "This protective effect of low IFN-γ in influenza differs from COVID-19, where inadequate secretion of IFN-γ by CD4+ T cells correlates with disease severity." (PMID 34987205, 2022). "Significantly increased tissue immunoexpression of Arginase, CD4, CD68, CD138, Perforin, Sphingosine-1, and IL-4 markers were observed in the COVID-19 group." (PMID 36430210, 2022). "COVID-19 vaccines have been shown to induce SARS-CoV-2 neutralising antibodies and elicit strong Th1-biased CD4+ responses in human." (PMID 34426655, 2022). "A pronounced decrease in CD4+ T cells, CD8+ T cells, and B cells has been reported in COVID-19 patients." (PMID 36034704, 2022). "In this study, the populations of CD4+ and CD8+ T cells were notably decreased in patients with COVID-19; this effect was particularly evident in severely ill patients requiring mechanical ventilation in the ICU setting." (PMID 35741107, 2022). "The significantly decreased number of CD3+ T cells, as well as CD3+CD4+ and CD3+CD8+ T cells, dynamically correlated with the severity of COVID-19 cases." (PMID 35632823, 2022). "Circulating SARS-CoV-2-specific CD4+ and CD8+ T cells have been detected in COVID-19 convalescent patients." (PMID 35205026, 2022). "Here, we compared serologic responses to SARS-CoV-2 RBD, full-length spike, and nucleocapsid in children with convalescent COVID-19, MIS-C, and HC and assessed for correlations with CD4+ T cell responses." (PMID 35044955, 2022). "In some COVID-19 patients, the feature of severe SARS-CoV-2 infection is lymphopenia with severely exhausted CD4+ T cells, CD8+ T cells, B cells, and NK cell counts." (PMID 35957855, 2022). "Populations exclusive to PBMC included CD4+ T cells that were expressors of CD95 (Fas) and PD-1, markers of apoptosis and exhaustion, a population that is described in peripheral blood of COVID-19 patients." (PMID 36275655, 2022). "In agreement, Nomah and colleagues showed worse COVID-19 outcomes in PLWH with viremia and CD4+ T-cell counts of less than 200 cells/μL." (PMID 35458478, 2022). "Pyroptosis-driven CD4+ T cell death following SARS-CoV-2 infection 65, 66 is supported by the increased serum levels of IL-1β and IL-18 in COVID-19 patients." (PMID 36313221, 2022). "CD4-CTLs in humans are reported in patients who respond to the viral infection, hepatic virus, CMV, DENV, and COVID-19 vaccine." (PMID 36353619, 2022). "The presence of specific memory CD4 and CD8 T cells with proliferation capacity up to ten months after recovery from COVID-19 have been reported." (PMID 35743605, 2022). "This indicates a CD4+ TCM and monocyte driven increased cytokines and chemokines in the active COVID-19 patients." (PMID 36532041, 2022). "Central memory (CM), effector memory (EM), and terminally differentiated effector CD4+ T cells were higher and naïve CD4+ and follicular helper T cells were lower in MIS-C and COVID-19 patients than in children with KD." (PMID 35495619, 2022). "It is important to put CMV colitis in the differential diagnosis of COVID-19 patients who present with hematochezia and diarrhea since SARS-CoV-2 decreases the numbers of CD4+ and CD8+ T lymphocytes, especially in severe cases." (PMID 35444867, 2022).
COVID-19 (continued). "In the current study we systematically studied SARS-CoV-2-specific proliferation of CD4 and CD8 T cells in recovered COVID-19 patients to better define the extent of their long-term memory cells." (PMID 36544780, 2022). "Immune suppression and decreased CD4+ and CD8+ T cells in COVID-19 patients make them more vulnerable to fungal infections." (PMID 36013183, 2022). "The relative numbers of T and B cells, CD4+ T cells, CD8+ T cells, CD4+FoxP3+ T cells and the mean signals for PD-1, CD27 and CD45RO in T cells were similar between COVID-19 patient and control samples." (PMID 35251032, 2022). "Lymphopenia was common in 25 COVID-19 patients, but after 2 weeks, the patients that cleared their infections presented restored numbers of CD3+, CD4+, CD8+ T cells and B cells." (PMID 35955740, 2022). "In COVID-19, higher responses of CD8+ T cells and CD4+ T cells, including circulating Tfh (cTfh) cells, against SARS-CoV-2 are associated with milder disease." (PMID 36437407, 2022). "In these mild COVID-19 cases, CD8+ T memory cell responses predominate over CD4+ T memory cell responses and, additionally, the memory CD8+ T cells specific for SARS-CoV-2 M and NP proteins exhibit the highest frequency of multiple cytokine production." (PMID 35833134, 2022). "In this prospective study of critically ill COVID-19 patients, the lymphocyte expression levels of CD markers for the examined T cell subsets (CD2, CD4, CD8, CD158d, and CD25) and CD127 as well as CD19 were lower in COVID-19 patients than in HCs." (PMID 35625671, 2022). "This explanation is supported by previous reports on the development of memory cells of CD4 and CD8 memory cells in asymptomatic and mild cases of COVID-19." (PMID 36142070, 2022). "We observed a lower median of absolute number: lymphocytes, including T lymphocytes (both CD4, and CD8), B lymphocytes, eosinophils and basophils, in active COVID-19 patients compared to the convalescent group." (PMID 35458548, 2022). "Lymphocyte count has revealed that CD4+ and CD8+ T cells are significantly reduced in both COVID-19." (PMID 35002519, 2022). "In convalescent mild and severe COVID-19 patients, a high production frequency of double- and triple-positive IFN-γ–, TNF-α–, and IL-2–producing CD4+ T-cells has been detected." (PMID 36389664, 2022). "An increased proportion of inflammatory CXCR4+ CD4 and CD8 T cells in the lungs of severe COVID-19 patients was shown, whereas in the lungs of moderate patients, an increased proportion of resident memory T cells was observed." (PMID 35757770, 2022). "In the current study, we evaluated CD4+ T and CD8+ T cell responses before and after the third dose of the COVID-19 vaccine and assessed the safety of vaccine booster shots at different times." (PMID 35632403, 2022). "On the other hand, CD73 expression is reduced in both, CD4+ and CD8+ T cells, in COVID-19 patients, corroborating with previous studies." (PMID 36248842, 2022). "Both CD4+ and CD8+ T-cell responses against spike protein of SARS-CoV-2 have been detected in COVID-19 patients, and this response is closely related to production of neutralizing antibodies in vivo." (PMID 36115859, 2022). "Antiviral CD4+ and CD8+ T cell responses in children convalescing from mild or asymptomatic COVID-19 remained higher than children with MIS-C, with the exception of frequency of spike-specific CD4+ T cells." (PMID 35044955, 2022). "These immunostimulatory properties of NAC further justify its use for COVID-19, since reduced levels of CD4+ and CD8+ T lymphocytes have been observed in critically ill COVID-19 patients." (PMID 35992575, 2022). "This clinical picture is noticed in COVID-19 patients, as described by the cumulative studies in our meta-analysis showing that following infection with SARS-CoV-2, CD4, and CD8 T-cell counts are reduced." (PMID 35572964, 2022). "By comparing the innate immune response between dengue and COVID-19, lymphopenia (CD3+, CD4+, CD8+) was found in both dengue and COVID-19." (PMID 36579259, 2022).
COVID-19 (continued). "A comprehensive mapping showed that functional CD4+ and CD8+ T cells, targeting multiple regions of SARS-CoV-2, are preserved in the resolution phase of both mild and severe COVID-19, and their magnitude correlates with the antibody response." (PMID 35205026, 2022). "SARS-CoV-2 spike (S) protein reactive T-cells were identified in immunocompetent (IC) patients suffering from moderate, severe, and critical COVID-19, and a dominance of CD4+ T-cell over CD8+ T-cell response was observed in severe and mild COVID-19 patients." (PMID 35744768, 2022). "In a cohort study in South Africa, among cases hospitalized with COVID-19, PWH with a history of immune compromise (CD4 count <200 cells/μL) were more likely to die in-hospital than those with CD4 counts of ≥200 cells/μL." (PMID 36570970, 2022). "Emerging data suggest that CD4+ and CD8+ T cell responses play key roles in controlling SARS-CoV-2 infection and COVID-19." (PMID 35764965, 2022). "Some notable statistically significant differences were a relative decrease in naive T cells (both CD4+ and CD8+) in progressive patients, as well as an increase in plasmablasts and dividing T & NK cells in COVID-19 patients vs controls." (PMID 35064122, 2022). "Regarding patients with COVID-19 and active tuberculosis (aTB), they exhibited decreased total lymphocyte counts, CD4 T cells specific against SARS-CoV-2 and responsiveness to SARS-CoV-2 antigens compared to patients with only COVID-19." (PMID 36090983, 2022). "Our findings reveal that the level of CD4/CD8 T-cells and IL-10 are reliable predictors of severity and mortality in COVID-19 patients." (PMID 35572964, 2022). "Our deconvolution analysis confirmed a lymphopenic profile (low CD4 and CD8 proportion) in COVID-19 patients upon admission to the ICU." (PMID 36371196, 2022). "We found higher frequencies of neutrophils, intermediate CD14+CD16+monocytes, activated HLA-DR+CD38+ CD4+ T cells, EM-like CD4+ and CD8+ T cells in COVID-19 respiratory compared to blood samples." (PMID 35589689, 2022). "Further studies on the immunogenicity, effectiveness and safety of COVID-19 vaccines should focus on various types of vaccines, PLWH with different CD4+ T cell counts, and booster vaccination, especially in countries and regions with heavy HIV burdens." (PMID 36146647, 2022). "The correlation between SARS-CoV-2 S1-specific antibody levels and spike-specific CD4+ and CD8+ T cell stimulatory indices was analyzed for vaccinated HCWs and COVID-19 patients." (PMID 35529867, 2022). "The contribution of the different CD4+ T cell profiles to both protective and harmful immune responses to SARS-CoV-2 has been rigorously analyzed in adults with COVID-19 but little is known in pediatric COVID-19." (PMID 35663467, 2022). "Consistently, a significant decrease in CD3+ T cells, CD4+ T cells, CD8+ T cells and natural killer cells in PBMCs indicates the severity of COVID-19 patients compared to moderate patients." (PMID 36389792, 2022). "It has been described that, besides CD4+ T cells, CD8 T cells also die in severely-affected COVID-19 patients compared to uninfected individuals." (PMID 36359755, 2022). "The CD4+ T cells dataset contains 6 mild COVID-19 patients, 8 severe COVID-19 patients, and 6 healthy donors, while the CD8+ T cells dataset has 15 mild COVID-19 patients, 22 severe COVID-19 patients, and 4 healthy donors." (PMID 35601483, 2022). "Lymphocyte subsets, particularly CD4+ and CD8+ T cells, were altered in COVID-19 patients, and lymphopenia has been reported as the primary symptom in most cases of COVID-19 patients." (PMID 35497875, 2022). "In CD8+ cells, we found a similar profile to that observed in CD4+; however, it is striking that CD95 (Fas) is overexpressed in nearly all CD8+ subpopulations of severe COVID-19 patients." (PMID 35743356, 2022).
COVID-19 (continued). "Overall, cross-reactive memory CD4+ T cells recognizing SARS-CoV-2 were detected in approximately 50% of individuals pre-pandemic and found to have functional properties against COVID-19." (PMID 36447262, 2022). "Patients with COVID-19 showed lower expression levels of lymphocyte surface CD markers during the first week for all the examined T subsets (CD2, CD4, CD8, CD158d, and CD25) as well as CD127 and B-cell marker CD19 compared to HCs (p < 0.001 for all)." (PMID 35625671, 2022). "Phospho-STAT3 levels in CD4 and CD8 T cells distinguished between healthy donors, moderate COVID-19, and severe COVID-19." (PMID 35421120, 2022). "In addition, this study reported lower levels of IFN-γ in CD4+ T cells of COVID-19 patients with severe symptoms compared to those with mild symptoms, suggesting that the infection may initially downregulate CD4+ and CD8+ T-cells, thereby decreasing IFN-γ production." (PMID 36363785, 2022). "Reductions in CD3+CD4+CD45RO−CD62L− and CD3+CD8+CD45RO−CD62L− T cell counts (as well as in the main fractions of B1 and B2 B cells) indicated a favorable outcome in COVID-19 patients in the acute stage of the disease." (PMID 35337053, 2022). "Children with MIS-C had significantly lower virus-specific CD4+ and CD8+ T cell responses to major SARS-CoV-2 antigens compared with children convalescing from COVID-19." (PMID 35044955, 2022). "Our findings suggest that CD4+ and CD8+ T-cells play an important role in restricting virus replication and suppressing the progression of COVID-19 and can be used to assess prognosis." (PMID 36033569, 2022). "Phenotypic assessment indicated that, in COVID-19 convalescent participants, SARS-CoV-2 CD4 responses displayed an early differentiated memory phenotype with limited capacity to produce interferon (IFN)-γ." (PMID 34140294, 2022). "Similarly, studies showed that less severe COVID-19 was linked with a recent exposure to seasonal Coronaviruses and demonstrated that the presence of cross-reactive T cells facilitated the expansion of SARS-CoV-2-specific CD8 and CD4 T cell responses during infection." (PMID 36142588, 2022). "A recent study of the immune response to the mRNA COVID-19 vaccine in SARS-CoV-2 naïve and recovered individuals showed a rapidly induced CD4 T cell response when compared to the gradually developing CD8 T cell response." (PMID 36544780, 2022). "The data collectively illustrates a significantly increased activation of both CD4+ and CD8+ T cells in COVID-19 patients at the initial sampling period that is sustained for some but not all markers in each subset." (PMID 36003367, 2022). "The immune dynamics of SARS-CoV-2 infection suggests that genetically encoded factors regulating the differentiation and function of CD4+ T cells, TFH, and germinal center B cells (GCB) likely influence the severity of COVID-19 disease." (PMID 35659055, 2022). "This systematic review and meta-analysis aimed to analyze T-cell subsets (CD4/CD8) and IL-10 in severe and fatal cases of COVID-19." (PMID 35572964, 2022). "Whereas no significant or very low percentages of ex vivo IL-22 or IL-17A-containing T lymphocytes were observed in healthy controls, IL-22+ and IL-17A+ single positive CD4+ and IL-17A+ CD8+ T cells were detected in COVID-19 patients." (PMID 35422799, 2022). "As for acute COVID-19 patients, the magnitude and polyfunctional profiles of ancestral SARS-CoV-2 spike-specific CD4 and CD8 T cell responses were comparable between convalescent individuals infected during the first or the second wave." (PMID 34931886, 2022). "Genes such as Bax and Bak are upregulated, indicating that CD4 and CD8 T cells from COVID-19 patients are more likely to die from apoptosis." (PMID 36359755, 2022). "Participants that responded to polyclonal stimuli by increasing IL-2 and IFN-gamma production and decreasing PD-1 expression in CD4+ and CD8+ T cells tended to develop mild COVID-19 symptoms." (PMID 35860236, 2022).
COVID-19 (continued). "Regardless of this substitution, even primary immunization with these m8Δ-based COVID-19 vaccines induced the formation of CD8+ and CD4+ effector memory T cells with the functionality to produce multiple cytokines." (PMID 36069348, 2022). "Nonetheless, there were modest but significant differences in the representation of a small number of V genes among CD4+ and CD8+ T cells of individuals with active COVID-19 versus sero(–) control individuals." (PMID 35943978, 2022). "Significantly reduced CD4+ and CD8+ T cell responses were observed in children with mild COVID-19 compared with those in adults." (PMID 36447262, 2022). "Compared to survivors, patients that died of COVID-19 had much lower lymphocyte count and the percentage of different lymphocyte cell subsets (like percentage of CD3+ T cells, Percentage of CD4 + T cells) was also lower." (PMID 36369012, 2022). "Transient depletion of both CD4+ and CD8+ T-cells has been reported in COVID-19 infection and EVD; however, peripheral T-cell counts are preserved in asymptomatic COVID-19 patients." (PMID 35890044, 2022). "Overall, higher values for T cell response were obtained for Ag2-Nil (CD4+ and CD8+) than Ag1-Nil (CD4+), indicating that both CD4+ and CD8+ T cells serve as cellular immunity induced by the COVID-19 vaccination." (PMID 36104370, 2022). "Cross-reactive CD4+ T cells that can cross-recognize SARS-CoV-2 and endemic HCoVs have been demonstrated in COVID-19–unexposed donors, COVID-19–recovered individuals, and vaccine recipients." (PMID 35061630, 2022). "In COVID-19 patients, the BTLA was significantly elevated on peripheral blood CD4+ and CD8+ T cells, when compared to the normal group." (PMID 35432324, 2022). "We observed that rhIL-7 significantly increased both CD4 + and CD8 + T cell proliferations in critically ill COVID-19 patients." (PMID 35246776, 2022). "Nucleocapsid peptide specific CD4 and CD8 T cells detectable at six months post infection reflect long lived natural immunity to COVID-19." (PMID 35743605, 2022). "Complementing these findings, CITE-seq analysis (STAR Methods) showed an increase in cycling and activated CD4+ and CD8+ T and NK cell populations in hospitalized COVID-19 cases, including CCR4hi Tregs." (PMID 35216673, 2022). "In a clinical study of 109 outpatients with COVID-19, the magnitude and quality of SARS-CoV-2-specific CD4+ T-cell response showed a shift, from IFNγ-producing cells to TNF-α-producing cells over time." (PMID 36032096, 2022). "Synergic action of COVID-19 patients’ plasma and hypoxia was needed to promote CD39 mRNA overexpression as well as elevated expression of CD39 in CD4+, CD8+ T cells and CD16+ NK cells." (PMID 35173744, 2022). "Trends for higher proportions of IFN-γ-containing CD4+ T lymphocytes and higher granzyme B MFI were observed in COVID-19 patients." (PMID 35422799, 2022). "There was a significant decrease in T cells, CD4+ T cells, CD8+ T cells, and NKT cells/μL at inclusion among COVID-19 patients relative to healthy controls." (PMID 36003367, 2022). "Lymphopenia with reduced numbers of CD4+ and CD8+ T cells is an obvious symptom in severe COVID-19 patients." (PMID 35874688, 2022). "The presence of protective SARS-CoV-2-specific memory B and T (CD4+ and CD8+) cells were observed 3 months after mildly symptomatic COVID-19, while specific memory T cells were present after mild or severe COVID-19." (PMID 36129963, 2022). "We found that, if compared to patients experiencing severe COVID-19, those recovering from severe COVID-19 display SARS-CoV-2-specific, highly polyfunctional CD4+ T cells with a Th1 and Th17 phenotype." (PMID 35887351, 2022). "In this study, we have applied several analytical approaches to explore the mechanism of gene expression based on CD4+ T cells and CD8+ T cells related to COVID-19." (PMID 35601483, 2022).